Y_RNA (Y RNA )
Gene: Miscellaneous RNA gene on chromosome 4 (1,683,420 to 1,683,529, reverse strand). Ensembl gene ENSG00000207009.
Homologues: Orthologues: chimpanzee Y_RNA (96% identical), macaque Y_RNA (95% identical), guinea pig Y_RNA (85% identical). Paralogues in human: RNY1P5 (88% identical), Y_RNA (85% identical), Y_RNA (84% identical), Y_RNA (83% identical), Y_RNA (82% identical), Y_RNA (81% identical), Y_RNA (80% identical), RNY1 (79% identical), Y_RNA (79% identical), Y_RNA (78% identical), RNY1P11 (77% identical), RNY1P14 (77% identical), and 97 more.